CDON (cell adhesion associated, oncogene regulated)
Description:
Together with BOC, forms a coreceptor required for sonic hedgehog (SHH) handoff to its patched receptor (PTCH1 or PTCH2), thereby allowing activation of the smoothened signaling pathway (By similarity). Binds to the dually lipid-modified Sonic hedgehog protein N-product (ShhN) downstream of SCUBE2 carrier and promotes its release to GAS1 (By similarity). ShhN is then directly transferred to patched receptor by GAS1 (By similarity). May also mediate cell-cell interactions between muscle precursor cells, promoting differentiation of myogenic cells (By similarity).
Synonyms: CDO; ORCAM; CDON1; Ihog; HPE11
Tractability: Antibody: its Gene Ontology location is reachable by antibodies, with high confidence; UniProt places it where antibodies can reach, with medium confidence; UniProt predicts a signal peptide or a membrane-spanning region.
Gene: Protein-coding gene on chromosome 11 (125,955,796 to 126,063,335, reverse strand). Ensembl gene ENSG00000064309.
Subcellular location: Cell membrane
Pathways (Reactome):
Signal Transduction: Activation of SMO; Ligand-receptor interactions
Developmental Biology: Myogenesis
Gene Ontology:
Molecular function: coreceptor activity; protein binding; protein carrier chaperone
Biological process: smoothened signaling pathway; cell adhesion; cell-cell adhesion; cellular response to vitamin D; negative regulation of biomineral tissue development; negative regulation of canonical Wnt signaling pathway; nervous system development; positive regulation of smoothened signaling pathway
Cellular component: plasma membrane; protein-containing complex
Genetic constraint (gnomAD): Loss-of-function variants: 65 observed, 109 expected, observed/expected ratio (o/e) 0.6, 90% interval 0.49 to 0.73. The upper end of that interval is the gene's LOEUF score, 0.73, which puts it in group 3 of 6, group 1 being the genes least tolerant of losing a copy. Missense variants: 1,361 observed, 1,551.9 expected, observed/expected ratio (o/e) 0.88, 90% interval 0.84 to 0.92. Synonymous variants: 534 observed, 568.55 expected, observed/expected ratio (o/e) 0.94, 90% interval 0.87 to 1.01.
Homologues: Orthologues: chimpanzee CDON (98% identical), macaque CDON (95% identical), dog CDON (84% identical), pig CDON (83% identical), mouse Cdon (82% identical), rabbit CDON (82% identical), rat Cdon (81% identical), guinea pig CDON (81% identical), tropical clawed frog cdon (58% identical), zebrafish cdon (45% identical). Paralogues in human: BOC (26% identical), IGDCC4 (19% identical), PRTG (18% identical), DCC (16% identical), ROBO2 (16% identical), SDK2 (16% identical), SDK1 (16% identical), NEO1 (16% identical), ROBO1 (16% identical), ROBO3 (15% identical), HMCN2 (14% identical), MXRA5 (14% identical), and 24 more.
Diseases named in the same sentence as CDON in open-access papers:
CDON is named in the same sentence as 43 diseases in open-access papers, as found by Europe PMC text mining. Sharing a sentence is not in itself a finding about the gene and the disease. The quoted sentences say what the papers report.
holoprosencephaly (13 papers, 2013 to 2025). Holoprosencephaly (HPE) is a complex brain malformation resulting from incomplete cleavage of the prosencephalon, occurring between the 18th and 28th day of gestation, and affecting both the forebrain and face, which results in neurological manifestations and facial anomalies of variable severity. "Mutations in the sonic hedgehog (SHH) signaling gene CDON have been recently reported in patients with holoprosencephaly and with pituitary stalk interruption syndrome (PSIS)." (PMID 34235642, 2021). "A compound heterozygous splicing CDON variant was identified in patients affected with bilateral coloboma of the iris, retina, and choroid and was also reported in holoprosencephaly (HPE) and pituitary stalk interruption syndrome." (PMID 36429029, 2022). "Cell adhesion associated, oncogene regulated (Cdon), is a ROBO-related cell surface protein associated with holoprosencephaly and is a receptor in the Hedgehog signaling pathway involved in early eye patterning." (PMID 36816119, 2023). "Impaired function of BOC, CDON, and GAS1 appears to underlie holoprosencephaly, both in humans and in mice." (PMID 29492654, 2018). "CDON−/− mice displayed the hallmark facial defects associated with microforms of holoprosencephaly, including lack of or solitary central maxillary incisors." (PMID 23704328, 2013). "Other gene mutations that relates to holoprosencephaly, including ZIC2, SIX3, TGIF1, CDON, FGFR1, CENPF and DHCR7, were not identified." (PMID 39859210, 2025).
colorectal cancer (4 papers, 2013 to 2022). A primary or metastatic malignant neoplasm that affects the colon or rectum. "For example, decreased CDON expression was also observed in a large fraction of human colorectal cancer and was associated with intestinal tumor progression in mice." (PMID 35631574, 2022). "We show that by inducing apoptosis in settings of SHH limitation, CDON expression constrains tumor progression, and as such, decreased CDON expression observed in a large fraction of human colorectal cancer is associated in mice with intestinal tumor progression." (PMID 23940460, 2013). "We thus analyzed whether the decreased expression of CDON seen in a fraction of human colorectal cancers has a causal implication in tumor progression." (PMID 23940460, 2013). "Decreased CDON expression is also observed in a large fraction of human colorectal cancers." (PMID 34895219, 2021). "As we mentioned, NEAT1 is upregulated in colorectal cancer; thus, the relationship between NEAT1 and CDON in EMPD may be completely different from that in other cancers." (PMID 34895219, 2021).
breast carcinoma (3 papers, 2013 to 2021). "Among significantly downregulated genes with promoter hypermethylation, CDON, ID4, and CPEB1 were associated with neuroblastoma, breast cancers, and hepatocellular carcinoma, respectively." (PMID 31796082, 2019). "CDON expression was decreased in a large fraction of colorectal and lung cancers and in a sizeable fraction of kidney and breast cancers." (PMID 23940460, 2013).
prostate carcinoma (3 papers, 2019 to 2022). A carcinoma that arises from epithelial cells of the prostate gland. "It was reported that CDON was involved in tumor cell growth and invasion in prostate cancer." (PMID 36008805, 2022).
brain malformation (2 papers, 2014 to 2023). "In case 7, brain malformations may be associated with CDON deletion, which is mutated in holoprosencephaly type 11." (PMID 25435912, 2014).
melanoma (2 papers, 2017 to 2021). A malignant, usually aggressive tumor composed of atypical, neoplastic melanocytes. "Currently, the functional characterization of frog cdon is lacking, but our expression predictions and analysis on other model organisms support potential roles of CDON in human melanoma." (PMID 29049289, 2017).
microphthalmia (2 papers, 2017 to 2022). Congenital or developmental anomaly in which the eyeballs are abnormally small. "Specifically, CDON and MITF are associated with eye size, deleterious mutations of which have been correlated with microphthalmia." (PMID 36192687, 2022).
neuroblastoma (2 papers, 2019 to 2025). Neuroblastoma (NB) is the most common solid, extracranial childhood tumor. "We found that the CDON regulatory region was occupied by NFIA and NFIB, aligning with findings that NFIB represses CDON in neuroblastoma cells." (PMID 39617063, 2025).
abducens nerve palsy (1 paper, 2021). Paralysis of the abducens nerve. "Here, we describe a novel heterozygous missense variant in the CDON gene associated with PSIS and unilateral facial and abducens nerve palsy." (PMID 34235642, 2021).
adenoma (1 paper, 2013). A neoplasm arising from the epithelium. "We next investigated whether CDON loss, as expected according to the pro-apoptotic activity of CDON, may enhance tumour cell survival at the transition from adenoma to adenocarcinoma." (PMID 23940460, 2013). "We observed a marked decrease in apoptosis rate in high-grade adenomas from CDON−/−APC+/1638N mice compared to that in size-matched CDON+/+APC+/1638N controls." (PMID 23940460, 2013).
cardiomyopathy (1 paper, 2021). A disease of the heart muscle or myocardium proper. "Several of the proteins impacted by myectomy (POSTN, MMP12, CDON, NAMPT, HAMP, LTA4H) were previously reported to be altered in cardiovascular disease, cardiomyopathy, or vascular disease with effects mediated through inflammatory mechanisms." (PMID 33804404, 2021).
colon adenocarcinoma (1 paper, 2013). "Consistent with a specific decreased expression in tumor cells, CDON immunohistochemistry in a panel of 45 human colon adenocarcinomas showed a marked decrease of CDON expression in epithelial tumor cells as compared to adjacent normal tissue." (PMID 23940460, 2013).
colorectal adenocarcinoma (1 paper, 2013). The most common type of colorectal carcinoma. "Interestingly, in this panel of colorectal adenocarcinomas, CDON expression is inversely correlated with tumor grade according to the TNM classification (χ2 test: p = 4.3E-5)." (PMID 23940460, 2013).
congenital diaphragmatic hernia (1 paper, 2022). A posterolateral defect of the diaphragm that allows passage of abdominal viscera into the thorax, leading to respiratory insufficiency and persistent pulmonary hypertension with high mortality. "Three genes located at 11q24.2 region, ROBO3, ROBO4, and CDON, are possible candidate genes for congenital diaphragmatic hernia." (PMID 35440058, 2022).
invasive breast carcinoma (1 paper, 2019). A carcinoma that infiltrates the breast parenchyma. "CDON mRNA expression was significantly lower in invasive breast carcinoma, invasive ductal breast carcinoma and invasive lobular breast carcinoma." (PMID 31058608, 2019).
skin cutaneous melanoma (1 paper, 2017). "We found complex results for 1 of the genes, CDON, as it appeared either up-regulated (>2%) or deleted (>3.5%) in uveal and skin cutaneous melanoma." (PMID 29049289, 2017).
thyroid cancer (1 paper, 2013). "Similar reduction of CDON expression was observed by dot blot array analysis in breast, ovarian, uterine, and thyroid cancers." (PMID 23940460, 2013).
tumor (7 papers, 2013 to 2025). "To do so, we investigated the possibility that CDON inactivation in mice may affect tumour progression by analyzing the effect of the CDON mutation on adenocarcinoma (ADK) formation in an APC+/1638N genetic background." (PMID 23940460, 2013). "For example, in low-malignancy breast cancers, PIEZO2 potentially exerts a protective effect through CDON-Hedgehog axis-mediated induction of proapoptotic signaling, thereby suppressing tumor growth." (PMID 41327436, 2025). "Both FRAS1 and CDON are involved in tumor progression, promoting tumor cell proliferation and colony formation." (PMID 38202722, 2023). "Our study reveals that METTL3-FRAS1 plays a crucial role in NSCLC cell proliferation, colony formation, and tumor growth through the regulation of CDON by cooperating YTHDF1." (PMID 36008805, 2022). "The result showed that CDON expression was upregulated in T1, T2, T3 and T5 tumor tissues compared to their corresponding normal tissues but T4 sample." (PMID 36008805, 2022). "MIA PaCa-2 cells express very low amounts of CDON at the protein level and are derived from a poorly differentiated tumor." (PMID 34235374, 2021). "We show that interfering with the Hedgehog–CDON interaction triggers CDON-dependent apoptosis in vitro, and tumor growth inhibition in vivo." (PMID 23940460, 2013). "In support of this notion, we present the preclinical demonstration that interference with the SHH–CDON interaction triggers a CDON-dependent apoptosis in vitro and tumor growth inhibition in vivo." (PMID 23940460, 2013). "While cyclopamine showed a significant tumor growth inhibitory effect, this antitumor effect was in part inhibited when CDON expression was silenced." (PMID 23940460, 2013). "Together this suggests that CDON expression is a constraint for tumor progression in the human pathology." (PMID 23940460, 2013). "The therapeutic relevance of CDON as a negative regulator of tumor growth is obviously minimal in the fraction of cancers with down-regulation of CDON." (PMID 23940460, 2013). "Nowadays, CDON was identified to participate in tumor progression." (PMID 36008805, 2022). "We thus investigated whether tumor cell death observed upon Smo antagonists may be somehow related to a CDON up-regulation and to a subsequent increased CDON-mediated cell death." (PMID 23940460, 2013). "Thus, tumor cell death induced by cyclopamine is, at least in part, due to the up-regulation of CDON expression." (PMID 23940460, 2013). "Reciprocally, we propose that the SHH expression, detected in human cancers and previously considered as a mechanism for activation of the canonical pathway in an autocrine or paracrine manner, actually provides a selective tumor growth advantage by blocking CDON-induced apoptosis." (PMID 23940460, 2013). "The three mRNAs, PGAP1, FKBP5 and CDON, may act as tumor suppressors in EMPD." (PMID 34895219, 2021). "Thus, CDON expression levels may provide opportunities to determine the differentiation status of PDAC tumors and predict the impact of CDON targeting on Shh release and tumor progression." (PMID 34235374, 2021). "Of note, the Hh co-receptor CDON and PTCH1 were expressed in the tumour cells at a level similar to that seen in the stroma, although this did not lead to increased expression of Hh downstream targets in the epithelial compartment." (PMID 27492255, 2016). "This beneficial effect may result from PIEZO2-induced caspase-9–dependent apoptosis mediated by CDON, a Sonic Hedgehog (SHH)-dependent receptor, thereby suppressing tumor growth." (PMID 41327436, 2025). "Moreover, we also validated the expression of CDON, YTDHF1, and METTL3 in collected NSCLC tumor samples." (PMID 36008805, 2022). "Furthermore, the pivotal nodes of the lncRNA–mRNA interaction network, including NEAT1, PGAP1, FKBP5 and CDON, were also validated by qRT–PCR and found to be downregulated in the EMPD tumor group." (PMID 34895219, 2021).
tumor (continued). "As we find that CDON is expressed in the tumour cell compartment, this leaves a possible tumour-promoting role for a non-canonical SHH/CDON/PTCH1 axis, acting independently of downstream Hh signalling." (PMID 27492255, 2016). "Thus together these data support the view that in SHH/CDON-expressing tumor cells, SHH constitutively inhibits CDON-induced apoptosis." (PMID 23940460, 2013). "Thus, targeting CDON/SHH interaction triggers tumor cell death and tumor growth inhibition by engaging CDON pro-apoptotic activity." (PMID 23940460, 2013). "According to the newly identified pro-apoptotic function of CDON in settings of SHH limitation, we thus investigated whether in SHH-expressing tumors, SHH does not (solely) activate the canonical signaling in stromal cells but also (or rather) blocks CDON-mediated tumor cell death." (PMID 23940460, 2013).
cancer (6 papers, 2013 to 2022). A tumor composed of atypical neoplastic, often pleomorphic cells that invade other tissues. "We show here that loss of CDON expression in cancers may be a selective advantage for survival in the presence of a limited concentration of SHH in the environment." (PMID 23940460, 2013). "CDON resembles in many aspects DCC (Deleted in Colorectal Cancer), the prototypical netrin-1 dependence receptor." (PMID 23940460, 2013). "In addition, we have shown that these traits confer to the pair SHH/CDON a key regulatory role in cancer progression as recently shown for the dependence receptor DCC." (PMID 23940460, 2013). "It was observed that CDON, YTHDF1 and METTL3 were highly expressed in cancer tissues compared to that of in corresponding normal tissues, suggesting that there was a positive relationship between FRAS1, CDON, and METTL3/YTHDF1." (PMID 36008805, 2022). "Similar pro-apoptotic effects of Fc-CDON3FbnIII were obtained with the colorectal HT-29, the pancreatic PANC-1, and the breast MDA-MB436 cancer cell lines, which all express CDON and SHH mRNA (Figure S6DE and not shown)." (PMID 23940460, 2013). "Development of a candidate drug interfering with Hedgehog–CDON interaction could be of potential benefit to the large number of patients suffering from cancers with high SHH levels, but not currently responding to therapies aimed at antagonizing the Hedgehog signaling pathway." (PMID 23940460, 2013).
infection (2 papers, 2014 to 2015). The state of being infected such as from the introduction of a foreign agent such as serum, vaccine, antigenic substance or organism. "Research in humans and murine models using infection with S. aureus as phenotypic trait have suggested different positional candidate genes, e.g., SEH1L, TNFAIP8, KLK, and CDON." (PMID 26612358, 2015).
adenocarcinoma (1 paper, 2013). A common cancer characterized by the presence of malignant glandular cells. "Of interest, CDON−/−APC+/1638N mice showed over 3.4-fold more of aggressive adenocarcinomas with muscularis or serosal invasion compared to CDON+/+APC+/1638N controls (p<0.01)." (PMID 23940460, 2013). "Moreover, whereas adenocarcinomas were detected in 46.4% of the CDON+/+APC+/1638N control mice, consistent with previous reports, the frequency of CDON−/−APC+/1638N mice with adenocarcinomas was markedly increased to 77.6% (p<0.05)." (PMID 23940460, 2013). "The incidence of adenocarcinomas was increased by more than 2.3-fold in CDON−/− APC+/1638N mice." (PMID 23940460, 2013).
bacterial infection (1 paper, 2022). "We identified five genes—S100PBP, AKAP1, USP6NL, CDON and SULF2—in five different patient subgroups that have been associated with viral and/or bacterial infection in the literature." (PMID 36517845, 2022).
CDON also shares sentences with these, for which no sentence is quoted: pituitary stalk interruption syndrome (3 papers); coloboma (2); hypogonadotropic hypogonadism (2); intestinal tumor (2); pancreatic cancer (2); cardiovascular disease (1); cervical cancer (1); colon cancer (1); congenital heart disease (1); congenital hypopituitarism (1); developmental delay (1); hepatocellular carcinoma (1); Intellectual disability (1); invasive ductal breast carcinoma (1); invasive lobular breast carcinoma (1); limb ischemia (1); lung carcinoma (1); non-small cell lung carcinoma (1); oral lichen planus (1); pituitary hormone deficiencies (1); progeria (1).